TRAPPC9 (trafficking protein particle complex subunit 9)
Diseases named in the same sentence as TRAPPC9 in open-access papers (continued):
Sharing a sentence is not in itself a finding about the gene and the disease.
Infertility (1 paper, 2024). "Consistent with our previous finding of infertility of male Trappc9-KO mice, Gene Ontology (GO) function analysis revealed alterations in reproductive processes and spermatogenesis." (PMID 38889014, 2024).
intellectual disability syndrome (1 paper, 2020). "At age 27, after advancement in genomic diagnosis, a seven base pair deletion resulting in a frameshift pathogenic variant in TRAPPC9 was found in his genome, which is associated with an intellectual disability syndrome." (PMID 32162493, 2020).
intracerebral hemorrhage (1 paper, 2025). A cerebrovascular disorder characterized by bleeding into one or both cerebral hemispheres including the basal ganglia and the cerebral cortex. "TRAPPC9 impacts nuclear factor κB signaling, and a SNP annotated to TRAPPC9 was associated with intracerebral hemorrhage." (PMID 40780200, 2025).
Lung Squamous Cell Carcinoma (1 paper, 2020). "TRAPPC9 encodes a protein that likely plays a role in NF-kappa Tumor Protein D52 is showed to be associated with Lung Squamous Cell Carcinoma." (PMID 32030321, 2020).
mental disorder (1 paper, 2020). A disease that has its basis in the disruption of mental process. "In addition, Ephx1 and several other genes (Pla2r1, Zmym6, Trappc9, and Nqo2) are annotated in the RGD as genes associated with neurodegenerative diseases and/or mental disorders." (PMID 32429546, 2020).
nonalcoholic fatty liver disease (1 paper, 2024). "Genome-wide analysis links Trappc9 to nonalcoholic fatty liver disease (NAFLD)." (PMID 38889014, 2024).
Stroke (1 paper, 2021). Sudden impairment of blood flow to a part of the brain due to occlusion or rupture of an artery to the brain. "And TRAPPC9 was proved to be related to stroke in study conducted among Japanese." (PMID 34586716, 2021).
cancer (7 papers, 2015 to 2025). A tumor composed of atypical neoplastic, often pleomorphic cells that invade other tissues. "For example, to date four TRAPP subunits are implicated in cancer: TrappC1 (Bet5), TrappC4 (Trs23), TrappC9, and TrappC10." (PMID 27066478, 2016). "In summary, NIBP/TRAPPC9 is highly expressed in cancer cell lines and tumor tissues." (PMID 25704885, 2015). "Further, five genes, ALMS1, TRAPPC9, CEP128, OR10T2, and CPVL, are among the SCLC genes but not in any of the common cancer gene lists, yet these genes were mutated in M9." (PMID 29050228, 2017). "These potential structural mutants may stem from the fusion of FAK and TRAPPC9 genes, according to the genomic profile of FAK in the panel of cancer cell lines described in the Encyclopedia or the CRC cohort in the TCGA database from our cBioPortal‐based analysis (data not shown)." (PMID 40959971, 2025).
neurodevelopmental disorder (5 papers, 2018 to 2022). A behavioral and cognitive disorder with onset during the developmental period that involves impaired or aberrant development of intellectual, motor, or social functions. "The TRAPPC9 gene was not familiar with neurodevelopmental disorders, but showed 4 mutations in GDD/ID children." (PMID 39817275, 2022). "Together these studies confirm autosomal recessive TRAPPC10 variants as a cause of human disease and define TRAPP-mediated pathomolecular outcomes of importance to TRAPPC9 and TRAPPC10 mediated neurodevelopmental disorders in humans and mice." (PMID 35298461, 2022). "In summary, TRAPPC6A potentially adds to a growing list of TRAPP complex proteins (TRAPPC2, TRAPPC9, TRAPPC11), including the closely related TRAPPC6B, involved in neurodevelopmental disorders." (PMID 29391579, 2018). "Studies of patient lymphoblastoid cells revealed an absence of TRAPPC10 alongside a concomitant absence of TRAPPC9, another key TRAPP II complex component associated with a clinically overlapping neurodevelopmental disorder." (PMID 35298461, 2022).
infection (2 papers, 2024). The state of being infected such as from the introduction of a foreign agent such as serum, vaccine, antigenic substance or organism. "To understand the mechanism of upregulation of Rab18 and TRAPPC9 expression in L. donovani infected macrophages, we focused on the modulation of miRNA expression as several intracellular pathogens alter the expression of host miRNAs to establish infection." (PMID 38412149, 2024).
neurological disorders (1 paper, 2025). "However, no human neurological disorders have yet been associated with combined variants in AP3B1 and TRAPPC9." (PMID 41300827, 2025).
TRAPPC9 also shares sentences with these, for which no sentence is quoted: tumor (5 papers); brain malformations (2); liver disease (2); schizophrenia (2); Alzheimer disease (1); Ataxia (1); autoimmune disease (1); Borjeson-Forssman-Lehmann syndrome (1); Brain atrophy (1); breast carcinoma (1); breast tumor (1); cerebral palsy (1); CHOPS syndrome (1); Chung-Jansen syndrome (1); Cohen syndrome (1); deafness (1); diabetes (1); ependymoma (1); gastric cancer (1); genetic disorders (1); glaucoma (1); hyperprolactinemia (1); leishmaniasis (1); Lissencephaly (1); Macrocephaly (1); movement disorder (1); neurodegenerative disease (1); Non-alcoholic Steatohepatitis (1); Periventricular heterotopia (1); prostate tumor (1).
A further 3 diseases each share a sentence with TRAPPC9 in 1 paper.